STIM1 (stromal interaction molecule 1)
Diseases named in the same sentence as STIM1 in open-access papers (continued):
Sharing a sentence is not in itself a finding about the gene and the disease.
Hypertension (13 papers, 2014 to 2025). The presence of chronic increased pressure in the systemic arterial system. "This idea is supported by previous evidence showing that upregulation of STIM-1 expression was associated with functional hyperactivation of STIM/Orai system in rats with ethanol-induced hypertension." (PMID 41009555, 2025). "Our findings indicate that, in SHR-A3, a single base change in Stim1 creates stroke susceptibility in the presence of hypertension." (PMID 32300198, 2020). "Not surprisingly, SOCE alteration in astrocytes has been reported to be associated with pathological states, such as hypertension and stroke, caused by a loss-of-function mutation in the STIM1 gene in a rat model." (PMID 31627428, 2019). "Increased activity of STIM1 can cause vasoconstriction and may affect the development or progression of hypertension." (PMID 40709334, 2025). "The STIM1 hypomorph exhibits cardiovascular defects, primarily hypertension and tachycardia." (PMID 37029630, 2024). "However, angiotensin-II-induced hypertension was significantly attenuated in the smooth muscle-specific STIM1-/- compared to wildtype animals, suggesting that STIM1 within the smooth muscle is a critical player in the role of angiotensin-II-induced hypertension." (PMID 32702049, 2020). "Vascular STIM1 plays opposing roles in the regulation of vascular tone; smooth muscle cell STIM1 is important for VSMC contractility, proliferation and the development of hypertension." (PMID 39917079, 2025). "The hypertension is due to the tachycardia which is not heart specific as it does not manifest in a heart-specific SOCE hypomorph strain but only in the global STIM1 hypomorph." (PMID 37029630, 2024).
Autoimmunity (12 papers, 2012 to 2025). The occurrence of an immune reaction against the organism's own cells or tissues. "Loss of Stim1 function in mice and humans is associated with antibody-mediated autoimmunity due to defects in T lymphocyte helper function to B cells." (PMID 32300198, 2020). "Since store-operated calcium entry is important in T cell-mediated autoimmunity, our results implied that polymorphisms of STIM1 may influence store-operated calcium signals which in turn involve the regulation of cytokine release and ESR/CRP expression." (PMID 23272049, 2012). "First, we analyzed WT and Stim1/2-deficient tissue resident Treg cells in female heterozygous Stim1/2Foxp3 mice that do not develop autoimmunity." (PMID 30862784, 2019). "Human biallelic loss-of-function (LOF) mutations in ORAI1 and STIM1 disrupt Ca2+ influx, causing a syndrome called CRAC channelopathy characterized by immunodeficiency, autoimmunity and other non-immunological findings." (PMID 38578569, 2024). "Here the authors show that STIM1 and STIM2, which activate the Ca2+ channel ORAI1, are essential for the differentiation of peripheral Treg cells into tissue-resident and follicular Treg cells and their ability to limit autoimmunity in mice." (PMID 30862784, 2019). "In Stim1/2Foxp3 mice, the lack of Tfr cells is an important contributor to their autoimmunity as depletion of B cells markedly reduced their autoantibody titers and ameliorated AIHA." (PMID 30862784, 2019).
gastric cancer (12 papers, 2016 to 2024). A primary or metastatic malignant neoplasm involving the stomach. "On the other hand, STIM1 was overexpressed in metastatic gastric cancer compared to the primary sites." (PMID 38532463, 2024). "STIM1 can promote gastric cancer progression and silencing STIM1 inhibits cell proliferation via arrest of the cell cycle at the G0/G1 phase and increases cell apoptosis in vitro." (PMID 34012400, 2021). "In the present study, we showed that DIM significantly upregulated STIM1 and decrease of ER Ca2+ levels, indicating that DIM cause STIM1 mediated SOCE activation and sustained cytoplasmic Ca2+ overload in gastric cancer." (PMID 33867841, 2021). "Xia reported that elevated expression of STIM1 promote cells proliferation and metastasis in human gastric cancer cells." (PMID 33867841, 2021). "Developing effective and selective activators targeting STIM1-mediated SOCE pathway will facilitate better therapeutic sensitivity of phytochemicals acting on SOCE in gastric cancer." (PMID 33867841, 2021). "The STIM1 effect on cell migration was also attributed to NFATc1 activation in both osteosarcoma and gastric cancer cells." (PMID 34069353, 2021). "The potential link of STIM1 to promoting apoptosis came from a recent investigation into the functional role of microRNA-185 in chemotherapeutic sensitivity of gastric cancer." (PMID 31252656, 2019). "STIM1 can also regulate autophagy in solid tumors such as gastric cancer via AMPK." (PMID 37932320, 2023). "In gastric cancer, downregulation of STIM1 also promotes apoptosis." (PMID 37932320, 2023). "These suggested that STIM1-mediated SOCE activation may become a promising therapeutic target to enhance effectiveness of DIM for gastric cancer therapy." (PMID 33867841, 2021). "Using the gastric cancer cell lines BGC-803 and MKN-45 cells, the decreased migration and invasion was associated with a decrease in the vimentin and fibronectin expression and an increased in E-cadherin expression upon knockdown of Orai1 and/or STIM1." (PMID 34069353, 2021). "Likewise, STIM1 was expressed at higher levels in gastric cancer cells than normal tissue, and again STIM1 knockdown inhibited cell migration and invasion." (PMID 27417567, 2016). "Some phytochemicals exert anti-cancer effect via inhibiting STIM1-mediated SOCE such as curcumin and phemindole 35, 36, by contrast, DIM activate STIM1-meidated SOCE to inhibit gastric cancer cells, the combination of these may reduce the effectiveness of anti-cancer." (PMID 33867841, 2021). "Ye found that 3,3’-Diindolylmethane (DIM) enhanced p-AMPK-CHOP-mediated ER stress through upregulation of STIM1-mediated SOCE, which in turn promoted autophagy in gastric cancer cells." (PMID 37932320, 2023). "Elevated ORAI1 and STIM1 expression upregulated MACC1 expression and promoted tumor cell proliferation, metabolism, migration, and invasion in human gastric cancer." (PMID 35406521, 2022). "Additionally, it has been shown that the SOCE inhibitors, SKF-96365 and 2-APB, or the genetic knockdown of STIM1 and ORAI1 suppress the LPS-induced COX-2 production in gastric cancer cells." (PMID 37371732, 2023). "STIM1 has no significant impact on the apoptosis pathway in gastric cancer." (PMID 38532463, 2024). "The activation of STIM1-mediated SOCE could increase sustained cytoplasmic free Ca2+ overload 31, the treatment of DIM for 24h enhanced the Ca2+ fluorescence intensity by Laser scanning confocal microscope in BGC-823 and SGC-7901 gastric cancer cells." (PMID 33867841, 2021). "Therefore, our study identified an effective way to activate STIM1-mediated SOCE, which may enhance the sensitivity of targeting Ca2+ homeostasis phytochemicals in gastric cancer." (PMID 33867841, 2021).
asthma (10 papers, 2006 to 2025). "In lungs from asthma and CF patients, STIM1-Orai1 co-localization was significantly increased, which is indicative of more Orai1 activation." (PMID 40589325, 2025). "The reduced gene expression of these proteins significantly inhibited chemotactic migration and smooth muscle cell proliferation, highlighting the role of STIM1 and Orai1 as targets for smooth muscle remodeling during asthma." (PMID 37841931, 2023). "Studies have shown that the expression of STIM1 and Orai1 proteins was positively modulated in smooth muscle cells of tracheal and bronchial tissue isolated from ovalbumin-challenged mice with asthma." (PMID 37841931, 2023). "Moreover, we propose that STIM1-Orai1 co-localization (Orai1 activation) can be used as a biomarker of inflammation in asthma, CF and other lung diseases." (PMID 40589325, 2025). "Interventions targeting calcium-regulated nodes (such as STIM1-Orai1 and Piezo1) may provide a new direction for asthma treatment beyond traditional anti-inflammatory strategies." (PMID 41437399, 2025). "Ca2+ sensor STIM1 drives airway hyperresponsiveness and airway smooth muscle remodeling in asthma." (PMID 37377967, 2023). "Because the present and previous results have demonstrated that SOCE tightly regulates the contraction, proliferation, and migration of ASM cells, STIM1 and Orai1 may be involved in mechanisms of the pathophysiology of airway diseases such as asthma and COPD." (PMID 22984609, 2012). "Our findings suggest that STIM1 and Orai1 may be important molecules responsible for airway remodeling in asthma." (PMID 22984609, 2012). "Given the importance of control of intracellular Ca2+ to airway smooth muscle contraction STIM1 may provide a potential therapeutic target for diseases characterised by increased smooth muscle contractility such as asthma." (PMID 16987424, 2006). "Studies have shown that the expression of STIM1 and ORAI1 proteins is positively modulated in the smooth muscle cells of tracheal and bronchial tissues in ovalbumin-challenged asthma models." (PMID 39664985, 2024). "In murine models of asthma, blocking CRAC channels effectively prevents Th2 cell-mediated responses, while mast cells from STIM1 or ORAI1 knockout mice exhibit impaired degranulation and reduced activation of transcription factors NF-AT and NF-κB." (PMID 39664985, 2024). "Reducing the expression of these proteins inhibits smooth muscle cell chemotaxis and proliferation, underscoring the role of STIM1 and ORAI1 in smooth muscle remodeling in asthma." (PMID 39664985, 2024). "It achieved this through interacting with miR-326 to regulate stromal interaction molecule 1 (STIM1), an endoplasmic reticulum membrane protein known that acts as a calcium sensor and stimulator of ASMCs remodeling and AHR in asthma." (PMID 38078005, 2023). "In contrast, STIM1-Orai1 co-localization was not altered in the alveolar regions, which is consistent with neither asthma nor CF being an alveolar disease." (PMID 40589325, 2025).
autoimmune disease (10 papers, 2013 to 2025). A disorder resulting from loss of function or tissue destruction of an organ or multiple organs, arising from humoral or cellular immune responses of the individual to their own tissue constituents. "STIM1 is required for the development and function of regulatory T cells, and STIM1 deficiency causes several autoimmune diseases and myopathy in human subjects and mouse models." (PMID 28494008, 2017). "We previously showed that SOCE is essential for pathogenic Th17 cell function as mice with T cell‐specific deletion of ORAI1, STIM1 or STIM2 were protected in Th17 cell‐dependent animal models of autoimmune diseases such as EAE and colitis." (PMID 32609955, 2020). "A recent study indicated that STIM1 inhibition in lymphocytes had beneficial effects for anaphylactic responses, ischemic brain infarction, and autoimmune disease." (PMID 28293066, 2017). "The greater reliance of pathogenic Th17 cells on STIM1 and OXPHOS may be exploitable for the treatment of autoimmune diseases in which pathogenic Th17 cells play an important role without affecting the antimicrobial function of non‐pathogenic Th17 cells." (PMID 32609955, 2020). "Interestingly, differential expression has been observed for the ORAI 1–3 and STIM 1 during T cells activation where the mRNAs were up-regulated and in Sjögren’s syndrome, an autoimmune disease, where the STIM1 and 2 proteins were reduced." (PMID 30543678, 2018). "Similarly, deletion of murine Stim1 severely impairs SOCE and the function of T cells, most evident in the inability of STIM1-deficient CD4+ T cells to mediate inflammation in animal models of autoimmune disease." (PMID 23922331, 2013). "Therapeutic strategies targeting these pathways are emerging, including SOCE inhibitors for autoimmune diseases, TRP channel modulators to skew polarization toward M2 phenotypes in fibrosis, and STIM1/Orai1 antagonists in clinical trials." (PMID 40487403, 2025). "A different STING antagonist that acts by modulating the interaction of STING with stromal interaction molecule 1 (STIM1), thereby blocking its trafficking from ER to Golgi, inhibited the progression of lupus, another photosensitive autoimmune disease, in human patients." (PMID 39350252, 2024).
lung carcinoma (10 papers, 2016 to 2024). "Two other studies reported the involvement of STIM1 in the cytotoxic effect of cisplatin in lung cancer cell models." (PMID 36142596, 2022). "The present ex vivo, in vitro and in vivo nude mouse data support the function of STIM1 as an oncogene, which is consistent with another lung cancer study." (PMID 31564210, 2019). "STIM1 was shown to be expressed in stromal cells in addition to lung cancer cells." (PMID 38532463, 2024). "They concluded that STIM1 might act as a negative regulator of apoptosis induced by cisplatin in lung cancer models." (PMID 36142596, 2022). "This study provides new insights into the molecular oncogenesis of lung cancer and suggests that STIM1 may be a potential molecular target for human lung cancer therapy." (PMID 27863410, 2016). "Unfortunately, how STIM1 works and the mechanism of STIM1 in lung cancer is unknown." (PMID 31564210, 2019). "In lung cancer, SOCE components including STIM1, ORAI1, and TRPC channels have been examined in a dataset of more than 2000 cases." (PMID 32046188, 2020). "The role of Ca2+ signaling through the SOCE pathway involving STIM1 and ORAI1 has been reported previously to affect the prognosis of cervical, colorectal, breast, esophageal, multiple myeloma, and lung cancers by affecting tumor growth, proliferation, metastasis, and survival." (PMID 32046188, 2020). "To investigate whether or not STIM1 has a potential role in lung cancer, we examined STIM1 expression by qRT-PCR assay." (PMID 27863410, 2016).
osteosarcoma (10 papers, 2017 to 2023). A usually aggressive malignant bone-forming mesenchymal neoplasm, predominantly affecting adolescents and young adults. "Based on their results, the authors suggested an association of STIM1 upregulation with the cisplatin-resistant phenotype in osteosarcoma." (PMID 36142596, 2022). "In an osteosarcoma cell line, Mungai and colleagues reported that knockdown of STIM1 in the setting of hypoxia is associated with reduced AMPK phosphorylation." (PMID 35179826, 2022). "After stably overexpressing STIM1 variants in the osteosarcoma U2OS cell line, we first examined how these variants influenced the SOCE function." (PMID 35008585, 2021). "In this study, we investigated the effects of STIM1-mediated SOCE on cell migration by overexpressing different STIM1 variants in an osteosarcoma cell line." (PMID 35008585, 2021). "Incubation at 1.5% O2 up-regulated activities of LKB1 in MEFs, and CaMKK2 in 143B osteosarcoma cells associated with Ca2+ influx and relocation of stromal interaction molecule 1- (STIM1) to the plasma membrane." (PMID 33513781, 2021). "It has been demonstrated that STIM1 is upregulated in chemo-resistant osteosarcoma tissues, compared with chemo-sensitive tissues." (PMID 36142596, 2022). "In osteosarcoma cell lines, the overexpression of STIM1 promotes the cell viability and cell migration, and it also contributes to the chemoresistance." (PMID 35008585, 2021). "In conclusion, the overexpression of STIM1 with normal function in an osteosarcoma cell line increased the cell migration ability." (PMID 35008585, 2021). "Mechanistically, STIM1, as well as Ca2+ entry, contributes to cisplatin resistance of osteosarcoma cells by inhibiting ER stress-mediated apoptosis." (PMID 31252656, 2019). "Consistently, real-time PCR results revealed that the mRNA expression of Stim1 was also increased in chemo-resistant osteosarcoma tissues as compared with chemo-sensitive osteosarcoma tissues." (PMID 28326487, 2017). "To determine the role of Stim1 in osteosarcoma, we first utilized immunohistochemistry to study the expression patterns of Stim1 in chemo-sensitive and resistant osteosarcoma tissues." (PMID 28326487, 2017). "Overall, the results demonstrate that elevated Stim1 expression restores cisplatin-inhibited Ca2+ influx and attenuates ER stress-mediated apoptosis in osteosarcoma cells." (PMID 28326487, 2017). "Collectively, these results suggest that Stim1 knockdown promotes ER stress-mediated apoptosis in cisplatin-resistant osteosarcoma cells." (PMID 28326487, 2017). "In summary, we demonstrate that Stim1-mediated SOCE protects osteosarcoma cells from undergoing apoptosis in response to cisplatin." (PMID 28326487, 2017). "Moreover, the protein expression of Stim1 determined by western blotting was similar to the immunohistochemistry and real-time PCR results, indicating that the increased Stim1 expression may be associated the chemo-resistance in osteosarcoma." (PMID 28326487, 2017). "In this study, we showed that Stim1 expression was significantly increased in chemo-resistant osteosarcoma tissues compared with chemo-sensitivity tissues." (PMID 28326487, 2017). "In the present study, we observed up-regulation of Stim1 in chemo-resistant osteosarcoma tissues and cisplatin-resistant osteosarcoma cells." (PMID 28326487, 2017). "To explore the impact of STIM1-mediated SOCE on the turnover of focal adhesion (FA) and cell migration, we overexpressed the wild-type and constitutively active or dominant negative variants of STIM1 in an osteosarcoma cell line." (PMID 35008585, 2021). "Similarly, upregulated STIM1 expression was found in chemo-resistant osteosarcoma tissues and cisplatin-resistant osteosarcoma cells." (PMID 31252656, 2019). "Our study suggests that targeting Stim1 may be a therapeutic strategy for osteosarcoma chemotherapy." (PMID 28326487, 2017).